PIK3R1 (phosphoinositide-3-kinase regulatory subunit 1)
Diseases named in the same sentence as PIK3R1 in open-access papers (continued):
Sharing a sentence is not in itself a finding about the gene and the disease.
melanoma (15 papers, 2012 to 2025). A malignant, usually aggressive tumor composed of atypical, neoplastic melanocytes. "Somatic mutations in the PIK3R1 gene, the gene involved in APDS2, were found in patients with carcinoma located in the ovary, large intestine, stomach, and malignant melanoma." (PMID 40370432, 2025). "Our study aimed to examine the associations between the clinical outcomes of malignant melanoma and some variants of SNPs in PIK3CA, PIK3R1 and VDR genes." (PMID 29100280, 2017). "Recent studies in melanoma have indicated that some components of the PI3K pathway (PTEN, MTOR, IRS4, PIK3R1, PIK3R4, PIK3R5 and NFKB1) are co-mutated in 17% of BRAF V600E mutant and 9% of NRAS mutant melanomas." (PMID 23006971, 2012). "Two of these DMGs, including ADCY1 and PIK3R1, are related to melanoma metastasis." (PMID 34134626, 2021). "Some variants of PIK3CA and PIK3R1 SNPs were studied in different type of tumor demonstrating an influence on prognosis but in malignant melanoma, PI3K polymorphisms have not been evaluated yet." (PMID 29100280, 2017). "In LN, MAPK3 (cf = 53), PIK3R1 (cf = 51), HRAS (cf = 46), PIK3R2 (cf = 45) and KRAS (cf = 44) are the top 5 cross-talk genes, and as expected most of these are already recognized melanoma markers." (PMID 26558755, 2015). "Our study is the first to evaluate this SNP rs3730089 in the PIK3R1 gene in melanoma patients and its impact on prognosis, even though no statistical association was found between genotype, OS and PFS." (PMID 29100280, 2017). "Furthermore, we first studied SNPs rs3730089 in the PIK3R1 gene and rs2699887 in the PIK3CA gene in melanoma patients, observing a trend of worse OS in homozygous recessive patients for the SNP rs2699887 in the PIK3CA gene vs. homozygous dominant and heterozygous genotypes." (PMID 29100280, 2017). "Interestingly, we identified variants in five new candidate genes, i.e., ARID1A, ARID2, SMARCA4, PIK3R1 and BAP1, which neither have been previously identified in melanoma BM nor reported in CNS metastases from other cancers." (PMID 33578810, 2021).
primary immunodeficiency (12 papers, 2018 to 2025). "Activated PI3 kinase delta syndrome (APDS) is a rare, inherited primary immunodeficiency characterized by gain-of-function mutations in the PIK3CD or PIK3R1 genes, resulting in hyperactivation of the PI3Kδ pathway and consequent immune dysregulation." (PMID 40978950, 2025). "Activated PI3K delta syndrome (APDS) is a rare primary immunodeficiency caused by gain-of-function (GOF) mutations in PIK3CD or PIK3R1, leading to immune dysregulation." (PMID 40951253, 2025). "One is the evaluation of the frequency and variability of PIK3CD and PIK3R1 mutations in Mexican populations, where genomic research in primary immunodeficiencies remains limited." (PMID 40951253, 2025). "Mutations in PIK3R1 were shown to cause primary immunodeficiency, and defects in or inhibition of the PIK3R1 gene may cause impaired T and B lymphocyte proliferation in vitro." (PMID 32508039, 2020). "Patients with activating mutations in PIK3R1 leading to an increased PI3Kδ activity also have primary immunodeficiency, and many studies, including large cohort studies, have defined new mutations in PIK3CD leading to activated PI3K delta syndrome (APDS) and expanded the phenotype of disease." (PMID 29563913, 2018). "Mutations in the PIK3R1 and PIK3CD genes can lead to activated phosphoinositide 3-kinase δ syndrome (APDS), a primary immunodeficiency affecting both humoral and cellular immunity, with some phenotypic similarities to CVID." (PMID 38028622, 2023). "More importantly, previous studies have reported that heterozygous mutation in PIK3R1 lead to activated phosphoinositide 3-kinase delta syndrome (APDS), which is a primary immunodeficiency and immune dysregulation." (PMID 35619939, 2022). "The next-generation sequencing (NGS)-based gene panel tests for primary immunodeficiency showed a heterozygous A>G substitution in the splice acceptor site at c.1300-2 position of PIK3R1, leading to exon-skipping." (PMID 34307262, 2021).
agammaglobulinemia (11 papers, 2017 to 2025). A decreased level of serum immunoglobulins. "The degree of involvement is associated with the type of inheritance, the more profound being in homozygous patients (agammaglobulinemia) and variable behavior (hypogammaglobulinemia) in patients with heterozygous mutations at the PIK3R1 splice site." (PMID 35990641, 2022). "Following the identification of agammaglobulinemia associated with PIK3R1 gene mutations in four patients from three unrelated families with autosomal dominant immunodeficiency and lymphoproliferation, heterozygous mutations of the PIK3R1 gene were discovered." (PMID 39044864, 2024). "The most frequent main genetic causes of predominantly antibody deficiencies in children infected with SARS-CoV-2 were BTK (n = 41), NFKB2 (n = 4), TNFRSF13B (n = 3), PIK3CD (n = 3), and PIK3R1 (n = 2)." (PMID 37559153, 2023). "Agammaglobulinemia with other inherited pattern were also concluded: AR agammaglobulinemia was associated with mutations in several other genes such as IGHM, IGLL1, CD79A, CD79B, BLNK, PIK3R1, and TCF3 genes; AD-related agammaglobulinemia was also found with LRRC8A and TCF3 gene mutations." (PMID 36140582, 2022). "Conversely, a recessive mutation in PIK3R1, resulting in loss of p85α expression, was reported in a patient with agammaglobulinemia and absent B-cell lineage." (PMID 27555459, 2017). "A similar clinical phenotype of agammaglobulinemia or hypogammaglobulinemia is observed in patients with hemizygous variants in BTK, biallelic variants in BLNK, heterozygous gain-of-function (GOF) PIK3CD, or loss-of-function (LOF) PIK3R1 variants, which all encode proteins involved in BCR signaling." (PMID 41607487, 2025). "In view of this patient’s clinical presentation and agammaglobulinemia, the differential diagnosis includes autosomal recessive forms of the disease (such as defects in IGHM, IGLL1, CD79A/B, PIK3R1, PIK3CD), as well as, more rarely, XLA." (PMID 41327272, 2025). "In our case, the homozygous mutation causing a premature stop codon in the PIK3R1 gene can explain agammaglobulinemia clinical findings although we could not analyze p85α, p50α and p55α protein expressions in our patient because of unavailability of techniques." (PMID 39044864, 2024). "Although XLA is the most common form of agammaglobulinemia, several other congenital agammaglobulinemias have been identified that are inherited in an autosomal dominant or recessive manner (μ chain, Igα, Igβ, λ5, E47, BLNK, PIK3R1)." (PMID 36359748, 2022).
COVID-19 (11 papers, 2021 to 2024). A disease caused by infection with severe acute respiratory syndrome coronavirus 2. "For instance, PIK3R1 was highly expressed in the total T cells of COVID-19 patients, which might lead to defective functions in the T cells and finally determine the pathogenesis of COVID-19." (PMID 35864512, 2022). "Following the use of the molecular docking analysis, we ultimately identified the core ferulic acid target proteins against OS and COVID-19, namely, STAT3, MAPK1, and PIK3R1." (PMID 36204096, 2022). "Using Venn diagram mapping, we further identified five core ferulic acid targets against OS and COVID-19 via autophagy, including MAPK1, TLR4, PIK3R1, STAT3, and PARP1." (PMID 36204096, 2022). "IL6, CXCL8, EGFR, FOS, PIK3R1, and NFKB1 were identified as common targets from the common pathways between cancers and COVID-19 (signaling by interleukins, TLR signaling, TNF-α signaling via NF-kB)." (PMID 34067609, 2021). "In brief, the scRNA-seq followed by the immune transcriptomic analysis indicated an activation state (through CD69 and HLA class II genes), chemotaxis (e.g., CCL3 and CCL4), an inflammatory state (e.g., NFKBIA, PIK3R1, S100A9, etc.)in T cells, especially in CD8+T cells, in COVID-19 cases." (PMID 33717140, 2021).
depression (10 papers, 2021 to 2026). "Topological analysis of the bioactive-target-pathway network indicated that MAPK1, PIK3R1, EGFR, AKT1, and SRC were the core targets enriched in crucial signaling pathways associated with treating depression by A. laxiflora." (PMID 38505421, 2024). "The upregulation of PIK3R1 in patients with depression may indicate a compensatory mechanism for lipid profile changes that could impact the neuroinflammatory pathway mediated by PIK3R1, a regulatory subunit 1 of inosine-3 kinase (PI3K) signaling pathway." (PMID 40343008, 2025). "Molecular docking analysis results exhibited that core targets of depression, such as SRC, EGFR, PIK3R1, AKT1, and MAPK1, bind stably with the analyzed bioactive compounds of A. laxiflora." (PMID 38505421, 2024). "Among the top 10 hub gene targets, MAPK1, AKT1, PIK3R1, EGFR, STAT3, and SRC were the most enriched targets in the selected KEGG pathway, suggesting their critical role in the pathogenesis of depression." (PMID 38505421, 2024). "The interaction pathway between CLM and depression is mainly enriched in PI3K-Akt, JAK-STAT, and NF-κB signaling pathway, PIK3R1, MAPK3, and AKT1 may be the potential targets of Stigmasterol, β-stiosterol, coumestrol." (PMID 37808199, 2023).
non-small cell lung carcinoma (10 papers, 2012 to 2025). A group of at least three distinct histological types of lung cancer, including non-small cell squamous cell carcinoma, adenocarcinoma, and large cell carcinoma. "Further, lower mRNA level of PIK3R1 is a high-risk factor in stage I non-small cell lung cancers." (PMID 31938022, 2020). "This aligns with our KEGG analysis showing PI3K-AKT pathway enrichment and previous reports of miR-486-5p/PIK3R1 axis in non-small cell lung cancer, pancreatic cancer and diabetic nephropathy." (PMID 40727105, 2025). "Mutations of PIK3CA, PIK3R1, and PIK3R2 are frequently detected in small-cell lung cancer (SCLC), non-small-cell lung cancer (NSCLC), hepatocellular cancer, and ovarian serous cystadenocarcinoma." (PMID 37596643, 2023). "miR-486-5p, suppresses cell proliferation in non-small cell lung cancer by regulating PIK3R1 expression and modulating AKT pathway activation." (PMID 31938022, 2020). "Nevertheless, it should be underlined that low PIK3R1 expression was a negative prognostic factor in multiple cancer types, including prostate, gastric, liver, and non-small-cell lung cancers as well as breast and uterine endometrial carcinomas." (PMID 39858051, 2025). "Kaempferol may regulate EGFR/PI3K/AKT and IGF1R/PI3K/AKT signaling pathways by targeting EGFR, IGF1R, PIK3R1 and Akt, and then play a role in the treatment of non-small cell lung cancer." (PMID 37533633, 2023). "Therefore, we believe that PIK3R1 may be regulated by miR-21-5p and participate in the malignant progression of non-small-cell lung cancer." (PMID 36688087, 2023). "Non-small cell lung cancer has GAB2 and PIK3R1 as two upregulated genes." (PMID 34764329, 2021).
Alzheimer disease (9 papers, 2017 to 2024). A progressive, neurodegenerative disease characterized by loss of function and death of nerve cells in several areas of the brain leading to loss of cognitive function such as memory and language. "Moreover, the analysis of exome sequencing data from over 10,000 subjects in the Alzheimer’s Disease Sequencing Project showed evidence of a functional variant of PIK3R1." (PMID 38396891, 2024). "The gene PIK3R1 has been shown to be involved in Alzheimer’s disease." (PMID 28558704, 2017). "In the brown module, the tissue-specific genes PIK3R1 and WNT5A participated in the axon guidance and Alzheimer’s disease." (PMID 36081461, 2022). "Moreover, based on the PPI network, PTPN1 has direct interactions with GSK3B, PIK3R1, and CAPN1 in the Alzheimer’s disease pathway." (PMID 38612872, 2024).
myocardial infarction (9 papers, 2016 to 2025). Gross necrosis of the myocardium, as a result of interruption of the blood supply to the area, as in coronary thrombosis. "We then observed that accounting for cardiomyocyte abundance reduced the differences in spatial expression both Zbtb16 and Pik3r1 between cmAKO and WT mice during myocardial infarction." (PMID 40705823, 2025). "By comparing the co-expression with ceRNA networks, five lncRNAs (SNHG9, LINC02202, UBAC2-AS1, PTCSC3 and myocardial infarction associated transcript (MIAT)) and 32 genes (such as PIK3R1, PTPRB) were found to be shared." (PMID 31534842, 2019). "Considering all the sub-networks and the related pathways pinpointed by NASFinder, PI3-kinase subunit alpha (PIK3CA) and PI3-kinase regulatory subunit alpha (PIK3R1) were identified as the proteins shared among all pathways, with the exception of myogenesis and myocardial infarction." (PMID 29529088, 2018).
type 2 diabetes (9 papers, 2013 to 2025). "SHORT syndrome is also characterized by partial lipodystrophy and severe insulin resistance (IR), leading to an early onset of type 2 diabetes, due to immediate post-receptor defect in insulin signaling (phosphoinositide-3-kinase regulatory subunit 1-PIK3R1)." (PMID 31583022, 2019).
atherosclerosis (8 papers, 2017 to 2025). A disease characterized by the build-up of fatty material and calcium deposition in the arterial wall resulting in partial or complete occlusion of the arterial lumen. "PIK3R1 downregulation and/or inhibition is shown to promote atherosclerosis." (PMID 40709334, 2025). "For example, PIK3R1 gene has 12 pathways, such as insulin resistance, relaxin signaling pathway, signaling pathway regulating stem cell pluripotency, fluid shear stress and atherosclerosis, AGE-RAGE signaling pathway in diabetic complication, focal adhesion, and so on." (PMID 36688087, 2023). "Among these, pathways such as Lipid and atherosclerosis (hsa05417), the PI3K-Akt signaling pathway (hsa04151), and the AGE-RAGE signaling pathway in diabetic complications (hsa04933) were enriched by five key target genes (MAPK1, MAPK3, AKT1, PIK3R1, IL6)." (PMID 40170727, 2025).
bladder cancer (8 papers, 2013 to 2024). "Our finding of a novel class of PIK3R1 mutations in the region of p85α responsible for PTEN regulation in bladder cancer is consistent with this additional function for p85α." (PMID 24367658, 2013). "Taken together our data indicate that there are complex genomic imbalances affecting the PIK3R1 region in bladder cancer and major alterations in expression of PIK3R1." (PMID 24367658, 2013). "Meanwhile, some tumor suppressor genes have been identified as direct and functional targets of miR-155, such as APC, VHL, PIK3R1, MLH1, all of where are frequently inactivated in bladder cancer due to promoter hypermethylation." (PMID 26657502, 2016).
cervical carcinoma (8 papers, 2013 to 2023). A carcinoma arising from either the exocervical squamous epithelium or the endocervical glandular epithelium. "From the genes differentially expressed between early and advanced stages of cervical cancer, six genes – three upregulated (BCL3, IGF2, and PIK3R1) and three downregulated (PTPN4, PERP, and DUSP1) were selected for validation by qRT-PCR." (PMID 24403257, 2013).
ocular depression (8 papers, 2020 to 2026). "Pathogenic variants in PIK3R1 are associated with the autosomal dominant SHORT syndrome, characterized by Short stature, Hyperextensibility, Hernia, Ocular depression, Rieger anomaly, and Teething delay." (PMID 36980880, 2023).
renal carcinoma (8 papers, 2015 to 2024). A carcinoma arising from the epithelium of the renal parenchyma or the renal pelvis. "PIK3R1 was also reported to negatively regulate the epithelial-mesenchymal transition and stem-like phenotype of renal cancer so its downregulation would lead to mobilization of cells and support establishment of metastases." (PMID 34956100, 2021). "Interestingly, no significant change was observed in the expression of HES1, GLI1 and NANOG, whereas the expression of CTNNB1 was markedly increased, suggesting that CTNNB1 may be involved in increased renal cancer stem-like phenotype caused by the down-expression of PIK3R1." (PMID 25757764, 2015). "To determine the effects of haploid knockout of PIK3R1 on the growth of renal cancer cells, we carried out colony formation assays for the wild type and mutant cells." (PMID 25757764, 2015). "In order to confirm the function of PIK3R1 in renal cancer cells, we analyzed the expression of ECAD, NCAD, VIM, SNAIL, and TWIST in normal renal cell (HK2) and RCC cell lines (786-O, A498, A704, and ACHN) with RT-PCR." (PMID 25757764, 2015). "Our data show that the reduction of PIK3R1 expression increases the motility and migration capacity of renal cancer cells." (PMID 25757764, 2015). "In addition, we induced deletion mutations of PIK3R1 in renal cancer cell lines (786-O and A-704 cell lines) using a CRISPR/Cas9 system to achieve haploid knockout of PIK3R1 which significantly decreased the expression of P85α." (PMID 25757764, 2015). "Taken together, PIK3R1 negatively regulated renal cancer cell migration and EMT in vitro." (PMID 25757764, 2015). "We then tested the role of PIK3R1 in renal cancer cell lines." (PMID 25757764, 2015). "Therefore, we hypothesize that the downregulation of PIK3R1 may confer renal cancer cells a selective advantage to translocate, colonize and develop as mRCC." (PMID 25757764, 2015). "In this study, we report that PIK3R1 expression is reduced in RCC, and that the reduction of PIK3R1 can result in EMT, enhance migration ability, and promote colony formation, tumor formation and cancer stem cell phenotype in renal cancer cells." (PMID 25757764, 2015). "Altogether, through the activation of the PI3K/AKT pathway which phosphorylates several cytoskeleton-regulating and EMT–activating proteins, the downregulation of PIK3R1 promotes migration and EMT in renal cancer cells." (PMID 25757764, 2015). "The downregulation of PIK3R1 promotes EMT, migration, and cancer stem cell phenotype in renal cancer cells and may contribute to the progression and metastasis of RCC by activating the PI3K/AKT/GSK3β/CTNNB1 pathway." (PMID 25757764, 2015). "Overall, PIK3R1 down-regulation in RCC promotes propagation, migration, EMT and stem-like phenotype in renal cancer cells through the AKT/GSK3β/CTNNB1 pathway, and may contribute to progression and metastasis of RCC." (PMID 25757764, 2015).
leukemia (7 papers, 2015 to 2024). A malignant (clonal) hematologic disorder, involving hematopoietic stem cells and characterized by the presence of primitive or atypical myeloid or lymphoid cells in the bone marrow and the blood. "Previous reports have described mutations in PIK3R1 in leukemia (6.4%), establishing PIK3R1 as an actionable gen in AML." (PMID 30303964, 2018).
pancreatic cancer (7 papers, 2019 to 2025). "Function annotation and prediction suggested that genetic variants in this locus might affect overall survival of pancreatic cancer patients by regulating PIK3R1 expression." (PMID 31059194, 2019). "PIK3R1 is the regulatory subunit of phosphatidylinositol 3-kinase (PI3K), which has critical roles in metabolic actions, and aberrant overexpression of PIK3R1 in pancreatic cancer cells suppresses lymphangiogenesis and lymph node metastasis." (PMID 38057344, 2023). "Recently, our team reported that circBFAR promotes the progression of PDAC via the miR-34b-5p/MET/Akt axis and that circNFIB1 inhibits lymphangiogenesis and lymphatic metastasis via the miR-486-5p/PIK3R1/VEGF-C axis in pancreatic cancer." (PMID 35189958, 2022). "miR-206 inhibits lymphangiogenesis in pancreatic cancer, and circNFIB1 interacts with miR-486-5p to regulate miR-486-5p/PIK3R1/VEGF-C and inhibit lymphatic proliferation, tube hyperplasia, and metastasis in pancreatic cancer." (PMID 36230535, 2022). "The higher expression of PIK3R1 suggested worse survival in two public datasets: Stratford Yeh Pancreatic GSE21501 and Pancreatic Cancer‐AU (PACA‐AU‐ICGC‐June 2016, Australian Pancreatic Cancer Genome Initiative)." (PMID 31059194, 2019).